COL9A1 (collagen type IX alpha 1 chain)
Description:
Structural component of hyaline cartilage and vitreous of the eye.
Synonyms: DJ149L1.1.2; EDM6; MED; STL4
Tractability: Antibody: its Gene Ontology location is reachable by antibodies, with high confidence; UniProt places it where antibodies can reach, with medium confidence; UniProt predicts a signal peptide or a membrane-spanning region.
Gene: Protein-coding gene on chromosome 6 (70,216,040 to 70,303,084, reverse strand). Ensembl gene ENSG00000112280.
Subcellular location: Secreted, extracellular space, extracellular matrix
Pathways (Reactome):
Extracellular matrix organization: Assembly of collagen fibrils and other multimeric structures; Collagen biosynthesis and modifying enzymes; Collagen chain trimerization; Collagen degradation; ECM proteoglycans; Integrin cell surface interactions
Developmental Biology: NCAM1 interactions
Signal Transduction: Signaling by PDGF
Gene Ontology:
Molecular function: carbohydrate binding; protein binding; protein homodimerization activity; extracellular matrix structural constituent conferring tensile strength
Biological process: animal organ morphogenesis; extracellular matrix organization
Cellular component: collagen type IX trimer; extracellular matrix; endoplasmic reticulum lumen; extracellular region
Genetic constraint (gnomAD): Loss-of-function variants: 94 observed, 125.49 expected, observed/expected ratio (o/e) 0.75, 90% interval 0.63 to 0.89. The upper end of that interval is the gene's LOEUF score, 0.89, which puts it in group 3 of 6, group 1 being the genes least tolerant of losing a copy. Missense variants: 1,125 observed, 1,136.2 expected, observed/expected ratio (o/e) 0.99, 90% interval 0.94 to 1.04. Synonymous variants: 442 observed, 386.55 expected, observed/expected ratio (o/e) 1.14, 90% interval 1.06 to 1.24.
Gene-disease validity (ClinGen):
ClinGen rates the evidence that COL9A1 causes each of these diseases.
Stickler syndrome, type 4 (autosomal recessive): Definitive.
Homologues: Orthologues: chimpanzee COL9A1 (99% identical), macaque COL9A1 (98% identical), rabbit COL9A1 (94% identical), dog COL9A1 (93% identical), pig COL9A1 (92% identical), guinea pig COL9A1 (91% identical), rat Col9a1 (90% identical), mouse Col9a1 (90% identical), tropical clawed frog col9a1 (67% identical), zebrafish col9a1a (47% identical), zebrafish col9a1b (46% identical). Paralogues in human: COL16A1 (43% identical), COL4A5 (36% identical), COL4A3 (35% identical), COL7A1 (34% identical), COL4A2 (34% identical), COL4A1 (34% identical), COL5A1 (33% identical), COL11A1 (33% identical), COL11A2 (33% identical), COL4A6 (32% identical), COL5A3 (31% identical), COL2A1 (31% identical), and 25 more.
Diseases named in the same sentence as COL9A1 in open-access papers:
COL9A1 is named in the same sentence as 58 diseases in open-access papers, as found by Europe PMC text mining. Sharing a sentence is not in itself a finding about the gene and the disease. The quoted sentences say what the papers report.
Stickler syndrome (19 papers, 2012 to 2025). Stickler syndrome is an inherited vitreoretinopathy characterized by the association of ocular signs with more or less complete forms of Pierre-Robin sequence, bone disorders, and sensorineural deafness (10% of cases). "Biallelic pathogenic mutations in COL9A1 have also been associated with Stickler syndrome with ocular abnormalities, alongside more common causes of Stickler syndrome caused by mutations in COL2A1 and COL11A1." (PMID 41153400, 2025). "Additionally, mutations in exon 9 of the COL9A1 gene have been linked to Kashin-Beck disease, congenital epiphyseal dysplasia, osteoarthritis, and Stickler syndrome." (PMID 38858754, 2024). "Interestingly, all three collagen genes (Col2a1, Col9a1, Col11a1) related to extracellular matrix degradation and enriched in expression in the peripheral retina are known to cause the Stickler Syndrome." (PMID 31108889, 2019). "By contrast, Stickler syndrome has the most collagens (six) linked to this syndrome (COL2A1, COL9A1, COL9A2, COL9A3, COL11A1, and COL11A2), followed by Ullrich congenital muscular dystrophy, with four collagens associated (COL6A1, COL6A2, COL6A3, and COL12A1)." (PMID 37189830, 2023). "Homozygous Type IX collagen variants (COL9A1, COL9A2, and COL9A3) causing recessive Stickler syndrome." (PMID 35198553, 2022). "Type 4, 5 and 6 Stickler syndromes (STL4, STL5 and STL6) have been attributed to homozygous or compound heterozygous mutations in the type IX collagen genes COL9A1, COL9A2 and COL9A3, respectively." (PMID 36140739, 2022). "The known causative genes of Stickler syndrome are COL2A1, COL11A1, COL11A2, COL9A1, COL9A2, and COL9A3." (PMID 34680973, 2021). "Mutations in COL9A1, COL9A2 and COL9A3 cause multiple epiphyseal dysplasia (MED), an autosomal dominant chondrodysplasia, Stickler syndrome." (PMID 34572492, 2021). "Stickler syndrome caused by COL2A1, COL11A1, and COL11A2 genes has a dominant inheritance, whereas COL9A1, COL9A2, and COL9A3 genes show a recessive inheritance." (PMID 34680973, 2021). "There were two children in our cohort with the rare form of Stickler syndrome from autosomal recessive collagen type IX disease (subject #3 and 4, both COL9A1‐related)." (PMID 33951325, 2021). "Since Stickler syndrome caused by COL9A1, COL9A2, and COL9A3 variants is very rare, most of the patients with Stickler syndrome are STL1 or STL2 patients if they have ocular abnormalities." (PMID 34680973, 2021). "More rare than the AD forms, biallelic pathogenic variants in COL9A1, COL9A2, and COL9A3 have been reported to cause recessive forms of Stickler Syndrome (Stickler Syndromes 4-6 [STL4-6])." (PMID 32867104, 2020). "To date, mutations in seven genes (COL2A1, COL11A1, COL11A2, COL9A1, COL9A2, COL9A3, and LOXL3) have been reported to cause Stickler syndrome." (PMID 32756486, 2020). "To date, multiple mutations in the collagen-encoding genes COL2A1, COL11A1, COL11A2, COL9A1, COL9A2, and COL9A3 have been associated with six genetically distinct types of Stickler syndrome." (PMID 28335520, 2017). "In humans, Stickler syndrome caused by mutations of COL2A1, COL11A1, COL11A2, COL9A1 and COL9A2, is one of the most common connective tissue disorders characterized by ocular, skeletal, orofacial and auditory defects." (PMID 26307084, 2015). "Stickler syndrome is commonly caused by mutations in different collagen genes, namely COL2A1, COL11A1 and COL11A2 (autosomal dominant inheritance) and COL9A1 and COL9A2 (autosomal recessive inheritance)." (PMID 26307084, 2015). "Since 2006, mutations in the collagen type IX alpha 1 (COL9A1) and collagen type IX alpha 2 (COL9A2) genes, encoding for type IX collagen, have been reported as causal for an autosomal recessive form of Stickler syndrome." (PMID 23592912, 2013).
Stickler syndrome (continued). "Indeed, mutations in COL2A1, COL11A1, COL11A2, COL9A1, COL9A2, and COL9A3 have been associated with Stickler syndrome and early-onset OA." (PMID 28335520, 2017). "In COL9A1-related autosomal recessive Stickler syndrome, the vitreous does not phenocopy the classic type 1 Stickler syndrome (COL2A1; membranous vitreous) or type 2 Stickler syndrome (COL11A1; beaded vitreous) patterns." (PMID 41153400, 2025). "These systemic syndromes can be caused by a series of genes, including NYX, CACNA1F, GRM6, and LRIT3, responsible for congenital stationary night blindness (CSNB); COL2A1, COL11A1, COL9A1, and COL9A2, responsible for Stickler syndrome; and FBN1, responsible for Marfan syndrome." (PMID 36980859, 2023).
multiple epiphyseal dysplasia (8 papers, 2012 to 2025). Multiple epiphyseal dysplasias (MED/EDMs) are characterized by epiphyseal anomalies causing joint pain early in life, recurrent osteochondritis and early arthrosis. "A female who had joint restrictions, genu valgum and avascular necrosis was identified to have a pathogenic variant in COL9A1 gene associated with multiple epiphyseal dysplasia." (PMID 35123515, 2022). "Additionally, mutations in COL9A1 are associated with multiple epiphyseal dysplasia, a hereditary condition characterised by early onset OA33." (PMID 38561399, 2024). "Multiple epiphyseal dysplasia (MED) may be caused by mutations of genes encoding collagen IX, namely COL9A1 (encoding α1 chain), COL9A2 (α2 chain), and COL9A3 (α3 chain), but such mutations are not the main cause of MED." (PMID 35883515, 2022).
osteoarthritis (7 papers, 2016 to 2024). A noninflammatory degenerative joint disease occurring chiefly in older persons, characterized by degeneration of the articular cartilage, hypertrophy of bone at the margins and changes in the synovial membrane. "This can be regarded as an antianabolic effect with an impact on OA, which is further supported by the finding that COL9A1 deficiency induces osteoarthritis-like pathology in mice." (PMID 33203447, 2020). "Another example is mice with collagen type IX alpha 1 gene inactivation, also called Col9a1 (−/−), which have been used to characterize the role of collagen type IX in osteoarthritis." (PMID 26837951, 2016).
breast carcinoma (4 papers, 2015 to 2022). "For instance, it was discovered the methylation level of COL9A1 reduced more evidently in tumors compared to that in the blood or healthy breast tissue, suggesting the association between COL9A1 and the risk of breast cancer." (PMID 34627275, 2021). "Several studies correlates COL9A1 with breast cancer and oral squamous cell carcinoma." (PMID 36009404, 2022). "These genes (COL9A1, ITGB8, ITGB6, TTYH1, RET, etc.)enriched in the cell adhesion may serve as important indicators of different types of breast cancer." (PMID 26273658, 2015).
myopia (4 papers, 2020 to 2025). "Second, patients with COL9A1 and COL9A3 mutations mainly present with moderate to severe myopia and rarely with retinal detachment." (PMID 32756486, 2020). "Therefore, we propose that SOX11 may directly or indirectly affect proteins with strong links to high myopia, such as COL9A1, COL2A1, and COL11A1, by affecting the expression or function of SOX4, ultimately causing the clinical phenotype of eoHM and dystrophy of cone-rod cells in CSS9 individuals." (PMID 40933692, 2025).
clubfoot (3 papers, 2023 to 2025). The most common congenital deformation of the foot, occurring in 1 of 1,000 live births. "Initially, genes associatedwith clubfoot (PITX1, TBX4, HOXA9, HOXD10, HOXD12,HOXD13, HOXA9, TPM1, TPM2, COL9A1, FLNB, CASP8,CASP10, UTX, CHD1, RIPPLY2, CAND2, WNT7) werescreened for potential variants." (PMID 38952703, 2024). "Mutations in genes encoding the ECM proteins COL9A1, COL9A2, COL9A3, COMP and MATN3, as well as the transmembrane glycoprotein involved in matrix organization, SLC26A2, have been associated with clubfoot." (PMID 37964341, 2023).
Kashin-Beck disease (3 papers, 2015 to 2024). Disabling osteochondrodysplasia with osteosclerosis, cone-shaped metaphysis, and shortening of the diaphysis. "In recent years, there have been many studies on the correlation between COL9A1 and Kashin-beck disease, congenital clubfoot and tumors." (PMID 39739914, 2024).
Autosomal recessive Stickler syndrome (2 papers, 2012 to 2025). "Autosomal recessive Stickler syndrome has been described in some families with mutations in COL9A1 (STL4) and COL9A2 (STL5) encoding type IX collagen." (PMID 23110709, 2012). "Maghsoudi and colleagues reported on the risk of retinal detachment in a cohort of 13 patients (ages 3 to 42; median age 14) with COL9A1-related autosomal recessive Stickler syndrome." (PMID 41153400, 2025).
metastatic tumor (2 papers, 2015 to 2022). "In contrast, seven other non-synonymous or frameshift mutations (in genes UGT3A2, PLCG1, OR10K1, COL9A1, MAGEA6, CNBD1 and LG14) were detected only in the metastatic tumor, indicating a selection and proliferative advantage of cells with the diverse genotype under sunitinib treatment." (PMID 26474454, 2015).
osteoporosis (2 papers, 2017 to 2018). A condition of reduced bone mass, with decreased cortical thickness and a decrease in the number and size of the trabeculae of cancellous bone (but normal chemical composition), resulting in increased fracture incidence. "Previous studies have shown that COL9A1 is associated with female osteoarthritis (OA), early onset OA and osteoporosis." (PMID 30577800, 2018). "COL9A1 may have a role in postnatal bone maintenance, as COL9A1+/− and −/− mice develop osteoporosis in association with an increased osteoclast number and activity in trabecular bone." (PMID 28335520, 2017).
Sciatica (2 papers, 2023 to 2025). Pain in the lower back and hip radiating in the distribution of the sciatic nerve. "Transgenic mice with a mutation in Col9a1 demonstrated progressive IVDD, likely affecting synthesis or assembly of non-fibrillar Col9a1 chains; while COL9A2 and COL9A3 variants were significantly correlated with sciatica and lumbar disc degeneration in a Finnish population." (PMID 37483952, 2023).
Arthritis (1 paper, 2006). Inflammation of a joint. "To understand the importance of CIX for cartilage integrity and stability and in the disease process of arthritis, we used a transgenic disruption of the col9a1 gene, leading to an absence of CIX, in two different genetic backgrounds (DBA/1 and B10.Q)." (PMID 16813664, 2006).
asthma (1 paper, 2021). "The underlying key genes in asthma pathogenesis and those regulated by treatment including Adipoq, HMOX1, SPP1, Cyp2e1, TNC, MB, MPO, Col9a1, Ckmt2, and Erbb4 were taken as examples to illustrate the positions and relationships with other points and midline in the figure." (PMID 33531915, 2021).
breast tumor (1 paper, 2019). "The levels of methylation in COL9A1 were decreased in breast tumor tissue and variants associated with OSCC occurrence." (PMID 30657779, 2019).
chondrodysplasia (1 paper, 2022). "Besides, P.7 carries pathogenic variants in both COL2A1 and COL9A2 mutations resulting in a more severe skeletal deformity and short-trunk dwarfism, while the other two patients (P.16, P.17) in our study only carrying COL9A1/COL9A2 mutation had very mild symptoms, with only mild chondrodysplasia." (PMID 35250876, 2022).
chondrosarcoma (1 paper, 2014). A malignant cartilaginous matrix-producing mesenchymal neoplasm arising from the bone and soft tissue. "Zhang and coworkers reported that the −560 to −357-bp region of the COL9A1 promoter is important for full COL9A1 promoter activity in the rat chondrosarcoma cell line." (PMID 25048791, 2014).
collagenopathy (1 paper, 2021). "Pathogenic variants for collagenopathy were uncovered in 10/12 children: COL11A1 (heterozygous) in six, COL2A1 (heterozygous) in two, and COL9A1 (homozygous) in two." (PMID 33951325, 2021).
dilated cardiomyopathy (1 paper, 2016). Cardiomyopathy which is characterized by dilation and contractile dysfunction of the left and right ventricles. "Upregulated COL4A5, COL9A1, COL21A1, and COL23A1 genes, encode collagens that have not previously been reported to be related to dilated cardiomyopathy." (PMID 27936202, 2016).
dwarfism (1 paper, 2013). "Our previous CCN2-transgenic mice under the control of the Col9a1 promoter show dwarfism several months after birth and smaller testes, but not so much difference in body length." (PMID 23555635, 2013).
femoral neck fracture (1 paper, 2014). Fractures of the short, constricted portion of the thigh bone between the femur head and the trochanters. "Interestingly, COL9A1 mRNA levels in OA chondrocytes were significantly different and were determined to be 6,200-fold lower than those in chondrocytes from patients with femoral neck fracture." (PMID 25048791, 2014).
joint disease (1 paper, 2021). "COL9A1 knockout mice develop normally without detectable abnormalities, but severe joint disease develops by approximately 9 months of age." (PMID 34572492, 2021).
mastitis (1 paper, 2021). Inflammation of breast tissue during lactation or postpartum due to an obstructed duct or infection. "The COL9A1 gene has been implicated in research involving identifying genomic regions and expression analysis of mastitis." (PMID 34691146, 2021).
postmenopausal osteoporosis (1 paper, 2022). Metabolic disorder associated with fractures of the femoral neck, vertebrae, and distal forearm. "COL9A1 and SOX9 are related to the genetic susceptibility of postmenopausal osteoporosis." (PMID 35198553, 2022).
Retinal dystrophy (1 paper, 2022). Retinal dystrophy is an abnormality of the retina associated with a hereditary process. "Ten families had variants in genes related to a syndromic disease with retinal dystrophy (COL9A1, CEP290, PCDH15, LRP5, PEX1, CFH, COL2A1 and COL11A1)." (PMID 35457050, 2022).
vitreous degeneration (1 paper, 2022). "The patients with mutations in COL9A1 were characterized by vitreous degeneration." (PMID 35456484, 2022).
cancer (6 papers, 2014 to 2025). A tumor composed of atypical neoplastic, often pleomorphic cells that invade other tissues. "We found tagSNPs in the FAT1 and COL9A1 gene nearby somatic mutations that drive cancer development were associated with oral malignancy occurrence." (PMID 30657779, 2019). "In this work, we identified five proteins, namely, Gal-1, Gal-9, MMP7, FASLG, and COL9A1, that based on their known function in endometrial and other cancers might represent useful early-stage EC biomarkers, upon a validation phase." (PMID 36009404, 2022). "However, no previous literature is available with regard to the role of COL9A1 in cancer." (PMID 24932297, 2014).
connective tissue disorder (3 papers, 2015 to 2022). A disease involving the connective tissue. "These children might be the carrier to the connective tissue disorder due to defective extracellular matrix as seen with COMP, COL2A1, COL9A1, COL9A2, etc. genetic mutation." (PMID 33870477, 2022).
tumor (3 papers, 2020 to 2023). "In addition, we observe that four genes (i.e., COL9A1, MSANTD2, LMBRD1 and RP11-1391J7.1) were differentially expressed between normal samples and tumor samples, and that COL9A1 was differentially expressed among different tumor stages." (PMID 34627275, 2021). "Additionally, the distinct pattern of Col9a1 expression among Neu tumor cells suggested the clustering of alveolar cells from gestation and lactation timepoints respectively." (PMID 32840210, 2020).
cardiac disease (1 paper, 2025). "While ECM remodeling is a well-recognized hallmark of HF, COL9A1, a collagen gene more commonly associated with cartilage biology, has rarely been studied in the context of cardiac disease." (PMID 40775796, 2025).
COL9A1 also shares sentences with these, for which no sentence is quoted: hearing loss (2 papers); infection (2); retinal detachment (2); cartilage disease (1); congenital heart disease (1); congenital stationary night blindness (1); COVID-19 (1); gastric cancer (1); glioma (1); heart failure (1); Hepatic fibrosis (1); ischemia (1); knee osteoarthritis (1); Kniest dysplasia (1); lumbar disc degeneration (1); Marfan syndrome (1); Marshal syndrome (1); melanoma (1); mitral valve disease (1); oral cancer (1); oral squamous cell carcinoma (1); ovarian carcinoma (1); pulmonary fibrosis (1); retinal disorder (1); rheumatoid arthritis (1); spondyloepiphyseal dysplasia (1); Talipes equinovarus (1); Ullrich congenital muscular dystrophy (1); vitreoretinal degeneration (1).